SRC (SRC proto-oncogene, non-receptor tyrosine kinase)
Diseases named in the same sentence as SRC in open-access papers (continued):
Sharing a sentence is not in itself a finding about the gene and the disease.
ovarian carcinoma (62 papers, 2009 to 2025). A malignant neoplasm originating from the surface ovarian epithelium. "Additionally, alterations in SRC gene expression have been linked to ovarian cancer manifestation, with its expression levels being associated with the occurrence and development of the disease." (PMID 38038814, 2023). "SRC signaling was active in both the eutopic endometrium of endometriosis patients and in in vitro models of endometriosis, and their findings suggested the novel therapeutic potential of Src inhibition (Src-pY416) for treating endometriosis-associated ovarian cancers (EAOCs)." (PMID 37033937, 2023). "Genes related to estrogen pathways, including ESR1 and ESR2, their coregulator PELP1, and the SRC, play a role in the induction and progression of ovarian cancer." (PMID 40362695, 2025). "EMT in ovarian cancer cells is dependent on RAC1 activation through the SOS1/EPS8/ABI1 complex, associated with increased MEK-ERK and SRC activation." (PMID 39354505, 2024). "In SKOV-3 ovarian cancer cells 5-HTR1E knockdown significantly increased SRC phosphorylation in SKOV-3 cells while in control cells serotonin inhibited pSRC in a dose-dependent manner." (PMID 37723479, 2023). "Taken an example of SRC (SRC Proto-Oncogene, Non-Receptor Tyrosine Kinase) gene, studies suggest that increased SRC expression results in hypoxic resistance to paclitaxel in ovarian cancer cells, and its inhibition using FV-429 can reverse this resistance." (PMID 38038814, 2023). "The SRC/mitogen-activated protein kinase (MAPK) signaling pathway drives the invasive growth of ovarian cancer cells." (PMID 36110943, 2022). "Next to ovarian cancer, also prostate cancer progression can be affected through inhibition of SRC myristoylation, highlighting its importance in various cancer types." (PMID 36226054, 2022). "In our study, we revealed with SRC that the expression was highly correlated in unchanged tissue and was decreased in ovarian cancer samples." (PMID 34207568, 2021). "Combination of the tyrosine kinase inhibitor sunitinib with the SRC inhibitor dasatinib showed synergistic anti-tumor activity in human ovarian cancer cells." (PMID 32927828, 2020). "Increased SRC activity has been found in ovarian cancer cell lines and late-stage, poor-prognosis ovarian tumors." (PMID 32927828, 2020). "Recently, SRC activity was suggested to play a role in adaptive resistance when ovarian cancer cell lines were treated with a MEK inhibitor." (PMID 31827720, 2019). "It has been reported that SRC is activated by EPHB4 in ovarian carcinoma models suggesting the role of SRC kinase in regulation of MYC." (PMID 31641103, 2019). "We set out to investigate potential mechanisms of resistance to the SRC inhibitor saracatinib (AZD0530) in ovarian cancer, with the aim to highlight potential combination therapies and treatment stratification markers for SRC inhibitors in this disease." (PMID 29435137, 2018). "Here, we have demonstrated that reduction in the expression of NF1 in two ovarian cancer cell lines results in activated MEK and ERK signalling, and is associated with decreased sensitivity to SRC inhibition." (PMID 29435137, 2018). "In this study we aimed to identify mechanisms of resistance to SRC inhibitors in ovarian cancer cells." (PMID 29435137, 2018). "It has also been reported that PTTG1 expression is predictive of sensitivity in ovarian cancer cell lines to SRC inhibition with saractinib (AZD0530)." (PMID 29435137, 2018). "SRC and SERPINE1 are reported to be essential for invasion and metastasis in ovarian cancer, phenomena that are associated with a poor prognosis." (PMID 28977939, 2017). "Western blot analysis revealed that CTCF protein expression was directly correlated with that of CTBP1 (R=0.69, P<0.01), SERPINE1 (R=0.56, P<0.05) and SRC (R=0.83, P<0.0001) in 18 fresh ovarian cancer specimens." (PMID 28977939, 2017).
ovarian carcinoma (continued). "Together, these data strongly suggest that CTCF mediates ovarian cancer metastasis by regulating the expression of metastasis-associated genes, including CTBP1, SERPINE1 and SRC." (PMID 28977939, 2017). "EGFR is one of the main kinases involved in activation of a number of downstream survival pathways, such as ERK, AKT and SRC, in ovarian cancer cells." (PMID 25928246, 2015). "Additionally, combined treatment with MEK1/2 and SRC inhibitors suppresses development of xenografts and prolonged survival of mice with ovarian cancer." (PMID 39354505, 2024). "IGF2BP1 is an invasive growth driver of ovarian cancer targeting the SRC/MAPK signaling pathway." (PMID 36110943, 2022). "Indeed, the increased myristic acid abundance was seen to enhance ovarian cancer in both mice and patients’ samples by inducing myristoylation of the oncogenic SRC pathway." (PMID 36226054, 2022). "This huge variation could influence the results of SRC expression and can explain elevated SRC protein levels in ovarian cancer patients observed by others." (PMID 34207568, 2021). "Dual inhibition of both MEK and SRC has more effective anti-tumor activity in ovarian cancer." (PMID 32927828, 2020). "Activation of the MEK/MAPK pathway is also observed in ovarian cancer following inhibition of SRC." (PMID 32927828, 2020). "Moreover, recent investigations have pointed out that adaptive resistance to MEK inhibitors in ovarian cancer cell lines was due to elevation of activated SRC." (PMID 31827720, 2019). "We have shown that a combination of SRC and MEK inhibitors synergistically inhibits the growth of saracatinib resistant ovarian cancer cells, and so we propose that ovarian cancer patients are more likely to respond to SRC inhibition in combination with MEK inhibition." (PMID 29435137, 2018). "Importantly, it has been reported that NF1 is the fourth most altered gene in epithelial ovarian cancer, highlighting the relevance of this genetic alteration when targeting SRC in this disease setting." (PMID 29435137, 2018). "Our data demonstrates different mechanisms by which MAPK signalling can become activated and result in resistance to SRC inhibition in ovarian cancer cells, highlighting the potential for combining SRC inhibitors with small molecule inhibitors of the MAPK pathway." (PMID 29435137, 2018). "Furthermore, SRC has also been identified as a potential driver of resistance to paclitaxel in ovarian cancer cells, and SRC inhibition enhances the antitumour and antiangiogenic effects of paclitaxel." (PMID 29435137, 2018). "Indeed, we observed a direct correlation between CTCF and CTBP1, SERPINE1, and SRC expression in cell lines, xenografted tumors and human ovarian cancer specimens." (PMID 28977939, 2017). "Similarly, activated SRC is found in 36% of primary ovarian cancers, and inhibiting SRC can reduce tumor growth, suggesting that in addition to blocking DNA damage repair, targeting both STAT3 and SRC in tumor cells can be an advantage of Niraparib over Olaparib." (PMID 36324587, 2022). "Therefore, PKC and/or SRC are maybe promising therapeutic targets in combination with CK2 inhibition in ovarian cancer and we will investigate this in future studies." (PMID 26871292, 2016). "Analysis of transcriptomic data from the TCGA HGSOC dataset suggests that SRC and GNAS expression may be associated with increased expression of EMT and cancer cell stemness markers, supporting the notion that these molecules may be able to drive EMT in ovarian cancers." (PMID 38097740, 2024). "These molecular docking findings indicated strong interactions between pachyman with SRC and STAT3 and the potential pharmacological targets against ovarian cancer." (PMID 37831733, 2023). "Treatment of ovarian cancer cells with sunitinib or dasatinib alone blocked phosphorylation/activation of STAT3 and SRC, respectively, but it had little effect on other signaling pathways." (PMID 32927828, 2020).
ovarian carcinoma (continued). "Several survival pathways are persistently activated in ovarian cancer cells, including STAT3, SRC, AKT, and MAPK signaling." (PMID 32927828, 2020). "In ovarian cancer, ITGBL1 promotes migration and adhesion through Wnt/PCP (planar cell polarity) and FAK/SRC (focal adhesion kinase/steroid receptor coactivator) signaling pathways." (PMID 32139701, 2020). "In PDX isolates of ovarian cancer cells, however, the expression and phosphorylation of ERBB1, ERBB2, c-MET, c-KIT, and c-SRC was reduced by drug combination exposure." (PMID 31380285, 2019). "Endoplasmic reticulum (ER) stress signaling was increased in sarcoma and ovarian cancer cells as judged by elevated PERK and eIF2α phosphorylation, whereas only in sarcoma cells was drug-induced activation of SRC observed." (PMID 31380285, 2019). "We have shown that a combination of SRC and MEK inhibition synergistically inhibits the growth of ovarian cancer cell lines, and that MEK inhibition is sufficient to resenesitize ovarian cancer cell lines with acquired resistance to saracatinib (AZD0530)." (PMID 29435137, 2018). "This work provides a preclinical rationale for the combination of SRC and MEK inhibitors in the treatment of ovarian cancer, and also highlights the need for biomarker driven patient selection for clinical trials." (PMID 29435137, 2018). "PHB, SRC, talin-1, tubulins and WDR1 are related to development of ovarian cancer resistance to paclitaxel and cis-platin." (PMID 29344361, 2018). "Similar to our findings, recent work has also demonstrated the utility of combining SRC and MEK inhibitors in the ovarian cancer setting, where the combination of selumetinib and saracatinib abolished Rac-1 mediated EMT of ovarian cancer cells." (PMID 29435137, 2018). "Our findings, to our knowledge, are the first to highlight the potential of combining SRC and MEK inhibitors in the treatment of platinum resistant ovarian cancer." (PMID 29435137, 2018). "To further evaluate the CTCF-mediated regulation of the expression of metastasis-associated genes, we analyzed the correlations between CTCF and SRC, CTBP1 and SERPINE1 gene expression in 255 human ovarian cancer specimens obtained from the GSE13876 database." (PMID 28977939, 2017). "In ovarian cancer cells, many survival pathways are persistently activated, including AKT, ERK, SRC and STAT3 signaling." (PMID 25928246, 2015). "On the other hand, IPA analysis showed several genes interacting with SRC or MYC, each of which was reported as a representative gene in oncogenic pathways of ovarian cancer." (PMID 20300634, 2010). "Based on current bioinformatics data, we might extrapolate that SRC and STAT3 were core pharmacological targets in pachyman treating ovarian cancer through regulating ferroptosis." (PMID 37831733, 2023). "Both SRC and STAT3 are regarded as potential targets in ovarian cancer treatment." (PMID 37831733, 2023). "Similarly, high expression of ITGBL1 facilitated cell migration and adhesion in ovarian cancer through Wnt/planar cell polarity (PCP) and focal adhesion kinase (FAK) /SRC signaling pathways." (PMID 35596183, 2022). "Our data shows decreased SRC mRNA expression in ovarian cancer patients compared to noncancerous changed and nonchanged." (PMID 34207568, 2021). "Instead, the concurrent activation of multiple signaling pathways, including PI3K/AKT/mTOR, SRC, MEK/MAPK, and JAK/STAT3, appears to be more common in ovarian cancer and may play an important role in ovarian tumor growth." (PMID 32927828, 2020). "This underscores the concept that simultaneous blockade of multiple cell growth/survival pathways, including JAK/STAT3, PI3K/AKT/mTOR, SRC and MEK/MAPK, may be required to achieve maximum anti-tumor activity in patients with ovarian cancer." (PMID 32927828, 2020).
ovarian carcinoma (continued). "Concurrent activation of multiple signaling pathways, including JAK/STAT3, PI3K/AKT/mTOR, SRC, and MEK/MAPK, appears to be more common in ovarian cancer and might be the critical force that drives ovarian cancer cells to proliferate and survive." (PMID 32927828, 2020). "SRC activity has also been implicated in resistance of ovarian cancer cells to anti-estrogen therapies, and a combination of the SRC inhibitor saracatinib (AZD0530) and fluvestrant resulted in increased cell cycle arrest and decreased survival of ovarian cancer cells." (PMID 29435137, 2018). "In addition, we performed IHC analysis to examine the expression of CTCF and SRC, CTBP1 and SERPINE1 in a different cohort comprising 40 ovarian cancer specimens." (PMID 28977939, 2017). "Additionally, we investigated the correlation of estrogen-related pathway genes (ESR1, ESR2, PELP1, and c-SRC) with hsa-miR-21 and hsa-miR-145 in non-affected ovary and ovarian cancer." (PMID 40362695, 2025). "To test the combined effect of these inhibitors on cell signaling pathways in ovarian cancer cells, we treated SKOV3 cells with sunitinib and dasatinib, alone or in combination, for 24 h, then measured the expression of the phosphorylated and total forms of STAT3, SRC, AKT, and MAPK by Western blot." (PMID 32927828, 2020). "The SAPPROC trial investigated the addition of the SRC inhibitor saracatinib (AZD0530) to weekly paclitaxel for the treatment of platinum resistant ovarian cancer; however, this drug combination did not provide any benefit to progression free survival (PFS) of women with platinum resistant disease." (PMID 29435137, 2018). "This phenomenon of rapid acquired or intrinsic resistance may explain the findings of the SAPPROC trial (NCT01196741), which investigated the use of the SRC inhibitor saracatinib (AZD0530) in combination with weekly paclitaxel, for the treatment of platinum resistant ovarian cancers." (PMID 29435137, 2018). "However this work has not been performed in ovarian cancer models of acquired resistance to SRC inhibitors." (PMID 29435137, 2018). "Besides, although inhibiting the SRC pathway or STAT3 had negligible effects on each other, combined treatment with both JAKi and SRCi led to substantial inhibition of both pathways and exhibited much stronger antitumor activities against human ovarian cancer cells." (PMID 32895373, 2020). "Although BOTs are not entirely recognized as malignant tumors and are not seen as a necessary process of transformation into ovarian cancer, in this study, we found some biomarkers related to EMTs, such as IL6, AKT1, MAPK3, SRC, TWIST1, and TGFB1." (PMID 33921111, 2021).
hepatocellular carcinoma (46 papers, 2009 to 2026). A malignant tumor that arises from hepatocytes. "To explore the key targets and signaling pathways of Ansofaxine hydrochloride for inhibiting hepatocellular carcinoma, we first dock SRC, GRB2, PIK3R1, AKT1, and EGFR, which are in the front of the core genes." (PMID 40809022, 2025). "Our findings revealed that METTL3 upregulates SRC expression in hepatocellular carcinoma through IRF1-dependent regulation." (PMID 40612868, 2025). "It is interesting to note that after visualization, the main core targets of mignonette in treating hepatocellular carcinoma are SRC, EGF, ESR1, AKT1, PI3KR1, AR, and CDK1." (PMID 38474604, 2024). "And the overexpression of SRC promotes the progression of hepatocellular carcinoma, and inhibiting the expression of SRC significantly suppresses the proliferation of liver cancer cells." (PMID 39022612, 2024). "The LINC00998-encoded short peptide SMIM30 can enhance the tumorigenesis of hepatocellular carcinoma through the regulation of the SRC/YES1/MAPK pathway." (PMID 37285335, 2023). "A separate analysis of the mutually independent roles of JAK2 and SRC in downstream signaling activation and cell fate, similar to studies done in pre-adipocytes and human hepatoma cells, would be of interest and value to resolve in further studies." (PMID 28223541, 2017). "In addition, the upregulation of SPP1 and SRC due to lower promoter methylation in liver carcinoma has been reported, which is in agreement with the findings of this study." (PMID 35452485, 2022). "Interferon-induced protein 44 like (IFI44L) is a tumor suppressor gene, which regulates the Met/SRC signaling pathway in hepatocellular carcinoma to affect cancer cell migration, lung metastasis, and drug resistance, and can be used as an ideal prognostic marker." (PMID 34384424, 2021). "Overexpression of EDIL3 in hepatocellular carcinoma could induce the phosphorylation of SRC, ERK, and SMAD2, leading to the activation of ERK and TGF-β signaling." (PMID 35096599, 2021). "Moreover, the underlying mechanism of EF24-suppressed invasion and migration of hepatocellular carcinoma has been shown to be through inducing the phosphorylation of SRC." (PMID 29780284, 2018). "Moreover, increased methylation-driven expression of the important oncogene SRC was identified in cholangiocarcinoma, hepatocellular carcinoma and colon adenocarcinoma, and SRC has previously been demonstrated to be active in cancer progression." (PMID 28178311, 2017). "According to Western blot and immune-histochemical analyses, src-related tyrosine kinases were discovered in large numbers in patients with liver cirrhosis and hepatocellular carcinoma, suggesting that SRC-RTK may have a role in the formation and progression of both diseases." (PMID 36297027, 2022). "It is particularly noteworthy that SRC and ESR1 seem to have a significant effect on the survival curve of patients with hepatocellular carcinoma." (PMID 38474604, 2024). "In hepatocellular carcinoma, IGF1R activates the downstream SRC signaling pathway to enhance the adhesion ability of hepatocellular carcinoma cells by increasing the phosphorylation level of FAK." (PMID 38292328, 2024). "In hepatocellular carcinoma, EPHB2 enhances cancer stem cell properties and drive sorafenib resistance by activating SRC/AKT/GSK3β/β-catenin signaling cascade." (PMID 36032135, 2022). "Network analysis of PPI in hepatocellular carcinoma (HCC) revealed that the metabolism and cytoskeletal biological process involved in HCC and cancer related proteins, such as SRC and PKM2, are hub nods." (PMID 35154607, 2021). "Finally, we showed that SRC is also a target of YAP in human hepatocellular carcinoma (HCC) cells and responsible for YAP-induced cell metastasis." (PMID 34862372, 2021). "Hepatocellular carcinoma samples displayed a dramatic surge in SRC expression compared with non-cancerous hepatic controls." (PMID 40612868, 2025).
hepatocellular carcinoma (continued). "Finally, we show that SRC is also a target of YAP and important for YAP to promote the migration of human hepatocellular carcinoma cells." (PMID 34862372, 2021). "Dasatinib, an SRC/ABL small molecular kinase inhibitor, has been approved by FDA due to the treatment of hepatocellular carcinoma, moreover, dasatinib inhibits cell proliferation in human esophageal squamous cell carcinoma through upregulating of the expression of MAD2." (PMID 32565740, 2020). "In hepatocellular carcinoma (HCC), NOD1 exerts an anti-tumor function by targeting the proto-oncogene SRC, leading to cell cycle arrest in the G1 phase and inhibition of the SRC–MAPK axis." (PMID 39329913, 2024). "In addition to that, five miRNAs (miR-124-3p, miR-34a-5p, miR-1-3p, miR-7-5p, and miR-99b-5p) were found in human cells that might target four hub genes (CXCL2, MMP9, SPP1, and SRC), which are related to inflammatory bowel disease (IBD) and hepatocellular carcinoma (HCC)." (PMID 37298833, 2023). "In hepatocellular carcinoma (HCC), CD155 also interacts with the SH2 domain of SRC (a nonreceptor tyrosine kinase) and further activates it." (PMID 36358792, 2022). "Dasatinib, an indirect STAT3 inhibitor against SRC/ABL, significantly facilitated anti-CTLA-4 immunotherapy in head and neck squamous cell carcinoma, while the combined blockade of IL-6 and PD-L1 remarkably inhibited the growth of pancreatic ductal adenocarcinoma and hepatocellular carcinoma (HCC)." (PMID 32972405, 2020).